FOXO6 (forkhead box O6)
Diseases named in the same sentence as FOXO6 in open-access papers (continued):
Sharing a sentence is not in itself a finding about the gene and the disease.
tumor (17 papers, 2014 to 2025). "The study also found that TNM stage, AFP and tumor differentiation degree, male, positive HBsAg, and FOXO6 were independent risk factors affecting HCC prognosis." (PMID 27227932, 2016). "Downregulation of FOXO6 promotes tumor invasion, because FOXO6 transcriptionally regulates Sirt6, which suppresses the secretion of MMP9." (PMID 38136293, 2023). "Previous study reported that FoxO1 and FoxO3 were two major participants involved in regulating tumor cell survival under Trastuzumab treatment, therefore, we evaluated the expression states of FoxO1, FoxO3, FoxO4 and FoxO6." (PMID 35835735, 2022). "Further analyses demonstrated associations among tumor size, tumor-node-metastasis (TNM) stage, AFP level, hepatitis B surface antigen status, degree of differentiation, and FOXO6 expression." (PMID 34123834, 2021). "The FoxO family, which consists of FoxO1, FoxO3, FoxO4, and FoxO6, is known as a tumor suppressor that limits cell proliferation and induces apoptosis." (PMID 32508033, 2020). "The members of the FOXO subclass (FOXO1, FOXO3, FOXO4 and FOXO6) are involved in a wide range of key biological processes including apoptosis, cell cycle, stress resistance, tumor resistance, differentiation, and metabolism." (PMID 31450545, 2019). "For the first time, we have shown that, among the various FOXO genes, only FOXO6 was frequently highly overexpressed in breast cell lines and tumours." (PMID 29484124, 2018). "In the highly invasive group, patients with FOXO6 overexpression were prone to death and tumor relapse (both P < 0.001)." (PMID 28404958, 2017). "FOXO6 may play an important role on tumor invasion, metastasis and prognosis." (PMID 28404958, 2017). "It is therefore also possible that FOXO6 elevation results in signalling activation that, in turn, reinforces phosphorylation and deactivation of FOXO tumour suppressors." (PMID 39499086, 2024). "The combination treatment transcriptionally upregulated tumor expression of SLC2A8 and FoxO6, important genes for glucose uptake, metabolism and redox balance." (PMID 34578801, 2021). "On the one hand, the widely studied FOXO1 regulates cellular function as a tumor inhibitor; on the other hand, FOXO3 and FOXO6 play important roles in promoting tumor growth and invasion and maintaining tumor survival." (PMID 34123834, 2021). "The tumor size, TNM stage, Alpha-fetoprotein (AFP) level, the presence or absence of hepatitis B surface antigen (HbsAg), and differentiation degree were related to FOXO6 expression level (all P <0.05)." (PMID 27227932, 2016). "The expression of FOXO6 in HCC tissues is significantly higher than that in normal and adjacent HCC tissues and is related to tumor size, TNM stage, AFP level, the presence or absence of HbsAg, and differentiation degree." (PMID 34123834, 2021). "Surprisingly, we found that FOXO6, but not FOXO1, 3, and 4, was frequently overexpressed in breast cell lines and tumours compared to normal cells, suggesting that this FOXO gene could act as an oncogene in human breast carcinogenesis." (PMID 29484124, 2018).
infection (3 papers, 2022 to 2024). The state of being infected such as from the introduction of a foreign agent such as serum, vaccine, antigenic substance or organism. "Specifically, cells were subjected to treatment with either a vehicle or the constitutively active form of FoxO6 (FoxO6-CA) at a concentration of 100 MOI (multiplicity of infection)." (PMID 38441531, 2024). "No change in FoxO6 and Kif15 expression was found in non‐CMs following Ang‐II treatment, regardless of infection with the FoxO6 adenovirus (Ad)." (PMID 37799807, 2023). "During the infection of Enterotoxigenic Escherichia coli (ETEC), forkhead box O6 (FOXO6) interacts with the m6A methylase METTL3 to promote the transcription of GPR161 (encoding G protein-coupled receptor 161), which in turn regulates the expression of intestinal β-defensin." (PMID 35804542, 2022).
cardiac diseases (2 papers, 2023 to 2026). "FoxO6 is an essential transcription factor that shows a strong association with the progression of cardiac disease." (PMID 37799807, 2023). "In future studies, we will further explore the role and significance of FoxO6 in the progression of heart disease." (PMID 37799807, 2023). "Combined with the excessive proliferation of fibroblasts and abnormal energy metabolism in CMs during HF, we suspect that FoxO6 plays an important role in heart disease." (PMID 37799807, 2023). "FoxO6 is expected to be an important intervention target for heart disease and even HF." (PMID 37799807, 2023). "Although FoxO6 is abundantly expressed in myocytes, its role in heart and cardiac diseases remains unclear." (PMID 37799807, 2023). "The regulatory role of FoxO6 in cardiac diseases remains unclear." (PMID 37799807, 2023).
FOXO6 also shares sentences with these, for which no sentence is quoted: cardiovascular disease (2 papers); Hypoglycemia (2); adenocarcinoma (1); Cognitive impairment (1); coronary atherosclerosis (1); diabetic cardiomyopathy (1); disc degeneration (1); E. coli infection (1); glioblastoma (1); hepatoblastoma (1); myocardial infarction (1); neurodegenerative disease (1); type 2 diabetes (1).